IL2 (interleukin 2)
Diseases named in the same sentence as IL2 in open-access papers (continued):
Sharing a sentence is not in itself a finding about the gene and the disease.
tumor (continued). "In addition, the immunoreactivity of IL-2 was observed in both tumor (black arrows) and immune cells (red arrows)." (PMID 34830445, 2021). "Others have reported superior tumor control by IL-7/IL-15 than IL-2–expanded T cells." (PMID 33156338, 2021). "For instance, TGF-β1 was enriched in tumor-derived EVs and was reported to induce regulatory T cells and to inhibit the proliferation of peripheral blood lymphocytes from healthy donors in response to IL-2." (PMID 32150875, 2020). "In our study, we could observe a striking difference in the tumor growth retardation between mice treated with untargeted and mice treated with targeted IL2, where the last managed to achieve a stronger and prolonged effect." (PMID 33110477, 2020). "The “standard TIL” isolation protocol (“selected TILs”), is based on an initial pre-Rapid Expansion Protocol (preREP) stage which comprise the resection of fresh tumor specimens into small segments, their fragmentation and culture under high-dose IL-2 (6,000 IU/ml) conditions for 3–5 weeks." (PMID 33680923, 2020). "To examine whether the observed superiority of IL-2/IL-15-expanded Vγ9Vδ2 T cells persists in conditions more resembling those of the tumor microenvironment, we repeated the cytotoxicity assays against ZOL-pre-treated FM-28 cells in hypoxia (1% O2)." (PMID 32983105, 2020). "Given that microcarcinoma PTC has less recurrent chance 21, the lower levels of IL-2 expression may reflect less pro-inflammatory infiltrates in the tumor lesions." (PMID 32368308, 2020). "Thus, our findings demonstrate a dual function of NKG2D for NK cell cytotoxicity; while NKG2D is a crucial trigger for cytotoxicity of tumor cells expressing activating ligands it is also capable to limit perforin production in IL‐2 activated NK cells." (PMID 32052406, 2020). "Oral administration of oligoderivatives of chitosan in mice with solid tumors of Sarcoma 180 and by intravenous administration in mice with Meth-A tumor induced tumor growth inhibition, increase levels of IL-1 and IL-2, and also a polarization to cytotoxic T lymphocytes, in the case of Meth-A." (PMID 32410869, 2020). "Similarly, in the AT3 model, NAM treatment was associated with increased tumor infiltration by CD4+ T cells expressing TNF alone, TNF and IFNG, as well as TNF, IFNG, and IL2." (PMID 32732875, 2020). "A co-incubation of NK cells with TKD/IL-2 resulted in significant upregulation of the CD94 density on NK cells that was accompanied by an increased cytolytic activity mediated by an upregulated granzyme B production against mHsp70+ tumor cells." (PMID 32443761, 2020). "RCC was classified as an “immunogenic” tumor based on the following characteristics: spontaneous regression of the tumor, high levels of T cell infiltration in the tumor, and reactivity to immunotherapy such as interleukin-2 (IL-2) and interferon alpha (IFN-α)." (PMID 32184905, 2020). "Consequently, collagen-redirected IL-2 reduced common side effects such as vascular leak syndrome and increased tumour infiltrating CD8+ T cells in an orthotopic breast cancer mouse model." (PMID 32481570, 2020). "This hypothesis was somewhat tested by examining the effect of molecules secreted by hADSCs-IL2 into CM on tumor cell growth, which were seen to have variable effects on the viability of the cancer cells." (PMID 32560387, 2020). "To test whether IL-2 was necessary for the anti-tumor activity driven by αCTLA-4, we inoculated WT mice with MCA205 and treated with αCTLA-4 in the presence or absence of a neutralizing αIL-2." (PMID 31924474, 2020). "Various autologous/syngeneic as well as allogeneic IL-2 gene-modified tumor cell vaccines have been investigated in preclinical and clinical studies for their potential in prophylactic and therapeutic application for the treatment of advanced and metastatic cancers like melanoma." (PMID 32917034, 2020). "IL-2 regulates activation and expansion of those immune cells that participate in tumor regression." (PMID 32651426, 2020).
tumor (continued). "Also, in this less TCR-dependent manner of tumor recognition, IL-2/IL-15-expanded cells performed better than IL-2-expanded cells." (PMID 32983105, 2020). "Taking into consideration these studies and our results, one could speculate that the IL-2/TGF-β blockade immunotherapy could also augment the chemotherapy-based anti-tumor responses outside of use in HSCT." (PMID 33138229, 2020). "Moreover, pemetrexed increased the secretion of cytokines, such as IFN-γ and IL-2, which stimulated a further increase in PD-L1 expression on tumor cells in a co-culture system and promoted T cell-mediated cytotoxicity when associated with atezolizumab." (PMID 32178474, 2020). "TILs are T cells isolated from tumor fragments, ex vivo-expanded and reinfused back into pre-conditioned patients under a non-myeloablative lymphodepletion chemotherapy with high doses of interleukin-2 (IL-2)." (PMID 33680923, 2020). "The presence of IL2 within the tumor through intratumoral IC may have a crucial role in driving this proposed T-dependent antibody response, as IL2 has been shown to be critical for CD40-mediated activation of naïve B cells by CD4 T cells." (PMID 32849544, 2020). "However, after the therapy with recombinant IL2 was approved by the FDA, it has been found that IL2 regulates not only effector T-cells but also regulatory T-cells (Tregs), which can inhibit an anti-tumor immune response." (PMID 32560387, 2020). "Moreover, metformin increases the number of CD8+ tumor-infiltrating lymphocytes and also protects them from apoptosis and exhaustion which is characterized by decreased production of IL-2, TNFα, and IFNγ." (PMID 32296640, 2020). "Importantly, Treg induction is less pronounced than with regular IL-2, and a direct comparison of Neo2/15 with equimolar recombinant IL-2 showed greater anti-tumour activity of the synthetic cytokine." (PMID 32019478, 2020). "Clinical application of IL-2 to exert anti-tumor effects while inhibiting the STAT5 signaling pathway might be an effective immunotherapy for SKCM." (PMID 32742470, 2020). "However, sorted PD-1+ TILs were found to downregulate PD-1 expression and regained their anti-tumour function upon in vitro culturing with IL-2." (PMID 32183246, 2020). "We sought to determine whether IL-2 controls GzmB expression in adoptively transferred tumor-reactive CD4+ T cells in vivo." (PMID 31924474, 2020). "Treatment with an IL-2 mutein reduces Tregs numbers and impairs tumour growth in mice." (PMID 32680511, 2020). "In line with this, OAd.TNFa-IL2 was created and it has shown great promise in vivo by curing 80% of Syrian Hamsters as a single treatment and 100% of the animals when given as a combination treatment with Tumor- infiltrating lymphocyte (TIL) therapy." (PMID 32225009, 2020). "However, several studies have also pointed out that insufficient activation of RCC tumor-infiltrating NK cells contributed to the failure of IL-2 treatment alone or in combination with other agents, such as IFNα." (PMID 32013092, 2020). "For example, IL-2 activates NK cells to decrease tumor masses and inhibit tumor cell metastases." (PMID 32600385, 2020). "Furthermore, NARA1leukin increases the in vivo half-life of IL-2 and redirects IL-2’s stimulatory activity to CD122high effector cells translating to potent anti-cancer responses in several preclinical tumor models." (PMID 33353953, 2020). "GM-CSF may enhance anti-tumor effects through direct activation and increased numbers of macrophages and granulocytes, and IL-2 is believed to activate NK cells, generating lymphokine-activated NK cells that augment ADCC." (PMID 32733795, 2020). "To validate whether ATP could be used as a sensor to determine NK cell-mediated cytotoxicity, we evaluated the lysis of tumour cells by NK cells treated with either IL-2 or DMSO." (PMID 32356467, 2020).
tumor (continued). "In contrast, administration of IL-2 and IFN-α has a low response rate and high toxicity associated with high doses, making targeted therapy and checkpoint inhibitors a better option currently for these tumours." (PMID 32610601, 2020). "The anti-CD20 antibody binds to tumor B-cells, which may lead to antibody-dependent cell cytotoxicity, and the IL2 moiety stimulates natural killer and T-cell immune responses." (PMID 32521744, 2020). "By using these IL-2-dependent T-cell lines infected with HTLV-1, we examined whether HTLV-1-infected T cells growing dependently on IL-2, progress to grow in IL-2-independent manner and whether they evolve into tumor-producing malignant cells." (PMID 32210945, 2020). "With the advent of commercially synthesized IL-2, T lymphocytes could now be cultured in large quantities, or in the context of an adjuvant, to boost the therapeutic effects of tumor-sensitized and adoptively transferred T lymphocytes." (PMID 32283684, 2020). "This reduction in IL6 secretion, may allow hADSCs-IL2 to have an inhibitory effect on tumor growth and proliferation compared to native hADSCs." (PMID 32560387, 2020). "Furthermore, IL-2 cytokine stripped from the membrane of NRP+I led to the activation of intratumoral cytotoxic T cells (CTLs) in the tumor microenvironment, which resulted in the synergistic effect of chemo-immunotherapy." (PMID 32210184, 2020). "However, TILs subjected to CTLA-4 blockade during tumor fragment cultures expanded to greater levels compared to TILs from tumor fragment cultures in IL-2 only (median 1,600 and 1,800-fold vs. 1,300 and 1,400-fold)." (PMID 32127601, 2020). "Although it was proposed that patients undergo a tumor biopsy to ascertain if their tumors were colonized by Salmonella-IL2 in the Phase I trial, the Institutional Review Board asks us to remove this from our protocol, thus it could not be performed." (PMID 32554977, 2020). "Therefore, the potential tumor-promoting effects of hADSCs-IL2 requires additional investigation in a range of different cancer contexts before preclinical application." (PMID 32560387, 2020). "Its application to the analysis of the joint behavior of IFN-γ, IL-2, IL-10 and IL-4 showed that the differences observed in the growth of M-406 tumor could be explained by the first two main components." (PMID 33312693, 2020). "NK cells can be activated by IL2 and gain tumor-cell killing capacity." (PMID 32560387, 2020). "Changes in gut microbiome leaded to changes in glycerophospholipid metabolism level, which may affect the expression of immune-related cytokines IFN-γ and IL-2 in the tumor microenvironment, resulting in a different therapeutic effect of PD-1 antibody." (PMID 32425919, 2020). "Importantly, these data suggest a systemic effect in the anti-tumor immune response with the addition of imiquimod; the uncertain lack thereof, as previously discussed, is a possible pitfall of intralesional IL2 monotherapy." (PMID 32455916, 2020). "Additionally, IL-2 augmented neutrophil cytotoxicity against tumor cells by inducing nitric oxide generation." (PMID 32422991, 2020). "Adoptive cell transfer (ACT) of T cells for tumor treatment often requires IL-2 administration." (PMID 32005809, 2020). "To reveal whether the senescence induction in tumor cells is dependent on IFN-γ/TNF-α produced by IL-2/IL-12/IL-18-stimulated γδ T cells, we neutralized IFN-γ/TNF-α by anti-IFN-γ antibody or anti-TNF-α antibody or both antibodies." (PMID 31947966, 2020).
tumor (continued). "Here we discuss the distinct roles of IL-2 and IL-15 in activating various functions of T and NK cells with a particular focus on the signals that contribute to the resistance of immune suppressive factors within the tumor microenvironment." (PMID 33266177, 2020). "Thus, the high expression of these cytokines in Syrian hamsters during OAd.TNFa-IL2 infection in vivo likely promoted the noted tumor growth limitation." (PMID 32225009, 2020). "Co-culture of lymphocytes with tumor cells induced a significant increment on the number of viable lymphocytes (p < 0.05), which may be explained by the natural production of IL-2 by both cell lines." (PMID 32850353, 2020). "Our data suggest that Ipilimumab may stimulate CTLA-4-expressing tumor cells to secrete IL-2, contributing to the establishment of a favorable immunologic microenvironment, that may support the action of Ipilimumab." (PMID 32850353, 2020). "The trial was divided into two different cohorts (due to safety reasons), where the patients in cohort (a) received in vitro expanded TILs and IL-2, while cohort (b) received in vitro expanded TIL, IL-2 and a unique DC vaccine program to boost in vivo the anti-tumor immune response." (PMID 32025850, 2020). "In the current work, we test the hypothesis that co-administered NKTR-214 can outperform IL-2 to improve the in vivo expansion, activation, and persistence of adoptively transferred effector T cells to improve anti-tumor efficacy." (PMID 32005809, 2020). "Besides molecule production by tumor residence cells, immune cells at the tumor site can modulate NK cell function by competing for IL-2 or inhibiting NK cell IL-2-mediated activation via cell-to-cell contact." (PMID 32391048, 2020). "Interestingly, a low concentration (10 μM) of metformin stimulated exhausted tumor-infiltrating CD8+ T cells to upregulate IL-2, TNF-α, and IFN-γ and potentiated anti-tumor activity." (PMID 33613560, 2020). "If the IL-2 effect consists in the activation of the host immune system, the role of IL-10 is not so clear, as IL-10 is a pleiotropic cytokine that at low concentrations exhibits tumor-promoting activity, while at high levels it shows an anti-tumor effect." (PMID 32013102, 2020). "Whilst A549 tumor cells were unaffected by hADSCs-IL2 CM, the proliferation of SH-SY5Y was significantly increased, whilst the proliferation of PC3 cells was modified both positively and negatively dependent upon the length of time hADSCs-IL2 had conditioned the media." (PMID 32560387, 2020). "Since mHsp70 has been found to serve as a target for Hsp70-peptide TKD/IL-2-activated NK cells in vitro and in vivo, time- and dose-dependent effects of irradiation with respect to the mHsp70 density on different human tumor cell lines were studied." (PMID 32276468, 2020). "Moreover, it also induced the secretion of cytokines, such as IFN-γ and IL-2, by activated peripheral blood mononuclear cells PBMCs that further stimulated the expression of PD-L1 on tumor cells, as demonstrated in a co-culture system." (PMID 32178474, 2020). "Cytokine-based therapies have been developed for cancer treatments, in particular human T cell growth factor, IL-2, has a main role in regulation of growth, differentiation and activation of tumor infiltrating lymphocytes (TLs) such as T cells and natural killers." (PMID 32268515, 2020). "Together, these studies demonstrated in two different tumor models that IL2-expanded autologous PBMC could recognize and kill tumor cells in vivo and the effect was enhanced by dual PD-1/CTLA4 blockade, but that tumor control was not durable." (PMID 33177175, 2020). "This comparative study demonstrates for the first time that TCR bypass stimulation i.e., γδ T cells stimulated solely with combined IL-2/IL-12/IL-18 is enough to induce γδ T cells that exhibit the same efficiency in anti-tumor activity as their counterparts after TCR crosslinking." (PMID 31947966, 2020).
tumor (continued). "Dinutuximab (ch14.18, a mAb against tumor-associated disialoganglioside GD2) has demonstrated activity against neuroblastoma cells; however, administration of the mAb alone was insufficient to prevent tumor progression, thus both GM-CSF and IL-2 were added to augment efficacy." (PMID 33381449, 2020). "Interestingly, dendritic cell populations represented an important fraction of the tumor immune cells in both ACT + IL-2 and ACT + NKTR-214-treated mice at an early time point (30.3% and 18.2%, respectively)." (PMID 32005809, 2020). "Thus IL-2 is critical for GzmB expression by endogenous tumor-infiltrating CD4+ T cells with little impact on other features of CD4+ T cell activation and differentiation in response to αCTLA-4." (PMID 31924474, 2020). "Greater IL-2 production and increased T cell tumor infiltration were observed." (PMID 35582435, 2020). "In addition to enzyme prodrug therapy, MSCs transduced with anticancer protein ligands, such as TRAIL, TNF-α, and NK-4, and immunomodulatory cytokines, such as IL-2 and IL-12, increase the survival rates of tumor-bearing rodents." (PMID 32764348, 2020). "In addition, IL-15 induced higher toxicity in BrHPP activated Vγ9Vδ2 T cells against different adherent tumor cells compared to IL-2." (PMID 32456316, 2020). "In the H3K27M+DMG orthotopic xenograft model derived from five independent patients (including spinal cord sources), GD2-targeted CAR-T cells could produce the cytokines inteferon(IFN)-γ and interleukin-2 (IL-2) and selectively killed tumor cells." (PMID 33679686, 2020). "Binding of CARs to cognate antigens expressed on the surface of tumor cells induces T cell activation and subsequent release of various cytokines, including interleukin-2 (IL-2), interferon-γ (IFN-γ), IL-6, and granulocyte macrophage-colony stimulating factor (GM-CSF)." (PMID 32320454, 2020). "Confirming what was described in the previous experiments, analysis of T cell populations revealed increased expansion and persistence of adoptively transferred Thy1.1+ CD8 T cells in spleen and tumor of mice treated with ACT + NKTR-214 compared to ACT + IL-2, both at days 7 and 14 days." (PMID 32005809, 2020). "Initial modern-day immune-boosting therapies used systemic application of interferon-α (IFN-α) or interleukin-2 (IL-2) and proved that injection of pro-inflammatory cytokines could induce durable anti-tumor immune responses in some cancer types." (PMID 32942725, 2020). "Overall, OAd.TNFa-IL2 hindered tumor growth in both tumor types." (PMID 32225009, 2020). "Therefore, effects of hADSCs-IL2 on tumor growth would depend on the cumulative concentration of TNF-α secreted." (PMID 32560387, 2020). "One early study incorporated IL-2 into multilamellar liposome drug carriers to develop a tumor vaccine adjuvant and showed that intravenous injection of IL-2 liposomes decreased hematologic toxicities in rats, indicating that NPs are capable of reducing drug toxicity." (PMID 32424240, 2020). "Investigations in mice suggested that combining IL‐2 with the closely related cytokine IL‐15, and IL‐18, could generate NK cells with antisolid tumor actions that were retained in vivo." (PMID 32480431, 2020). "The anti-tumor activity of NK cells may be potentiated by cytokines, particularly IL-2, which was initially considered to be a promising anti-neoplastic drug for its capacity to boost T cell and NK cell anti-tumor activity." (PMID 32272610, 2020). "In addition, external environmental agents can activate oncogenic STAT3/STAT5 signaling in malignant T cells leading to the release of IL-2 and other cytokines that eventually result in tumor progression." (PMID 33333886, 2020). "Darleukin represents a targeted form of IL2, capable of selective accumulation at the tumour site." (PMID 32539805, 2020).